DPP4 (dipeptidyl peptidase 4)
Diseases named in the same sentence as DPP4 in open-access papers (continued):
Sharing a sentence is not in itself a finding about the gene and the disease.
cancer (314 papers, 2000 to 2026). A tumor composed of atypical neoplastic, often pleomorphic cells that invade other tissues. "Cancer stemness, a driver of aggressiveness and treatment resistance, has been linked to DPP-4 activity." (PMID 40282969, 2025). "A meta-analysis of 72 randomized controlled trials (RCTs) has shown that individuals with T2DM treated with DPP-4 inhibitors face a significantly reduced risk of developing cancer compared to those receiving a placebo or other chemotherapeutic agents." (PMID 39333445, 2024). "While initial concerns about pancreatic cancer risk have been largely addressed, the benefits of DPP-4 inhibitors in both cancer treatment and prevention are increasingly recognized." (PMID 39333445, 2024). "Compared to T2DM, very few studies have addressed impacts of DPP4 genetic variants on cancer risk or progression." (PMID 37533175, 2023). "Several cancer-associated adipocyte subtypes, namely DPP4+ adipocytes in visceral adipose and ADIPOQ+ adipocytes in subcutaneous adipose, are identified." (PMID 37454080, 2023). "A study on endometrial carcinoma showed a positive association between DPP-4 expression and cancer cell proliferation, invasion, and tumorigenicity." (PMID 35933633, 2022). "Meta-analysis of site-specific cancers associated with DPP-4 inhibitors use in 12 RCTs and 13 observational studies did not reveal elevated cancer risk in DPP-4 inhibitors’ users." (PMID 33562380, 2021). "Here, we showed that DPP4 expression was upregulated and positively associated with age, cancer stage, and nodal metastasis in patients with LUAD." (PMID 33614513, 2021). "The conclusion by clinical analysis when examining the association between DPP-4 inhibitor and cancer incidence is influenced by diverse factors." (PMID 34063285, 2021). "High expression levels of DPP4 in some types of cancer patients can increase susceptibility to severe acute respiratory syndrome coronavirus (SARS-CoV)-2 infection and further cause cytokine storms." (PMID 34359286, 2021). "FAP is a very closely related enzyme to DPP-4 and exhibits higher levels in some cancers, especially in cancer-associated fibroblast." (PMID 34063285, 2021). "In this study, using different datasets, we demonstrated the expression of DPP4 in healthy tissues and pan-cancers, showing the risk of different cancer types towards SARS-CoV-2 infection according to DPP4 expression levels." (PMID 33614513, 2021). "In the Cancer Genome Atlas (TCGA) test dataset, eight genes were detected, and six of them were survival associated (DPP4, FFAR4, RASA3, RASGRF1, XCR1, and STX11)." (PMID 34760708, 2021). "In this review, we discuss the risk of cancer associated with anti-diabetic therapies, including DPP-4 inhibitors and SGLT2 inhibitors, and the role of catechol-o-methyltransferase (COMT), AMPK, and cell-specific glucocorticoid receptors in cancer biology." (PMID 32498358, 2020). "Some recent studies have suggested that the use of dipeptidyl peptidase-4 inhibitors (DPP4i) is associated with cancer development." (PMID 28811622, 2017). "When patients with different cancers were grouped according to DPP4 levels, lower serum DPP4 levels were significantly associated with shorter survival." (PMID 27936466, 2017). "It is also noteworthy that lung fibroblasts from older donors were generally more activated, similar to cancer associated fibroblasts, with increased Fapα and/or Dpp4 expression." (PMID 21912590, 2011). "DPP-4 enzyme associates with several proteins, so it plays a crucial role in cancer biology and may be considered as a useful marker for different tumors." (PMID 40786041, 2025).
cancer (continued). "A meta-analysis of 72 randomized controlled clinical trials, however, encompassing 70,000 enrolled participants, did not substantiate significant associations between the use of DPP-4 inhibitors and cancer development in comparison with the use of other active drugs or placebo." (PMID 40277890, 2025). "One of these compounds, Kaempferol, which is a chemical found in fruits and vegetables and might reduce cancer risks and development, presents strong associations with DPP4, 1 of 17 enriched genes by querying Translator." (PMID 38271343, 2024). "The frequency of these CD26/DPP4+ cells was associated with a poor prognosis in cancer but could be related to greater stemness and persistence, as has been shown in immune system cells." (PMID 39000199, 2024). "Consistent with their spatial organization, cancer cells drive the transition of detoxification-associated iCAF (Detox-iCAF) towards immunosuppressive extracellular matrix (ECM)-producing myCAF (ECM-myCAF) via a DPP4- and YAP-dependent mechanism." (PMID 38561380, 2024). "The catalytic effect of DPP-4 is reported to be associated with cancer progression." (PMID 35933633, 2022). "Higher DPP4 levels were associated with higher survival in all cancers combined." (PMID 35600378, 2022). "Taken together, these data suggested that expression of DPP4 may be closely associated with immune infiltration in specific cancers patients, which might also contribute to the cytokine storm in SARS-CoV-2 infected patients." (PMID 33614513, 2021). "Accordingly, DPP4 expression is linked with tumorigenic behaviour in a variety of cancer types." (PMID 33143089, 2020). "Deviant expression of DPP4 is associated with tumor aggressiveness in different cancers." (PMID 30450337, 2018). "The expression of DPP4 is linked to the carcinogenesis of many malignant tumors." (PMID 27936466, 2017). "The association of DPP4 with patient survival has been addressed widely in different carcinomas." (PMID 27936466, 2017). "Additionally, our results showed that DPP-4 inhibitors may lower the risk of developing cancer compared to sulfonylureas." (PMID 40290515, 2025). "However, the influence of metformin and dipeptidyl peptidase-4 inhibitors (DPP4is) on the risk of cancers remains unclear." (PMID 41300987, 2025). "However, DPP-4 inhibitors may also be associated with adverse effects, including skin lesions, immune reactions, and possibly cancer." (PMID 39274465, 2024). "Additionally, metformin use, either alone or in combination with DPP-4 inhibitors, was associated with a lower risk of new-onset metastasis in diabetic patients with concomitant cancer, with hazard ratios of 0.84 (95% CI: 0.79–0.90) and 0.87 (95% CI: 0.80–0.95), respectively." (PMID 38254789, 2024). "However, studies focusing on the impacts of genetic variants of DPP4 on cancers are very rare." (PMID 37533175, 2023). "However, it is not only in our study that higher DPP4 might be associated with better survival in various cancers such as head and neck malignancies." (PMID 37521469, 2023). "Finally, we investigated whether the suppression of autophagic induction was involved in the antigrowth effects of metformin in DPP-4-deficient cancer cells, similar to the effect of the mTOR inhibitor rapamycin." (PMID 37760498, 2023). "The results were consistent across pre-defined subgroups stratified by type of DPP-4 inhibitor, type of cancer (including pancreatic and thyroid cancer), drug for comparison, trial duration, or baseline characteristics." (PMID 40277890, 2025). "Insufficient evidence exists regarding the potential effect of the new types of diabetes medications, known as SGLT-2 inhibitors, DPP-4 inhibitors, and GLP-1 agonists, on the risk of cancer." (PMID 40290515, 2025). "CD26+ cancer stem cells have been found and the role of DPP4 in the development of metastases has been highlighted." (PMID 39861115, 2025).
cancer (continued). "DPP-4 plays a multifaceted role in cancer biology, including its involvement in cell differentiation, adhesion, immunomodulation, and apoptosis." (PMID 40282969, 2025). "In the LUSC group, we can get a similar conclusion, in addition, DPP4, PARP11, and TCP11L2 were found to be positively correlation with the cancer-associated fibroblasts (CAFs) and endothelial cells." (PMID 39949782, 2025). "Studies have shown that DPP4 is upregulated in various tumors and contributes to cancer development." (PMID 38890707, 2024). "Vigorous efforts have been invested in identifying CSC markers, and recently, dipeptidyl-peptidase 4 (DPP4, also known as CD26) has been reported as a marker of stemness (CSCs) in several cancers and has been associated with distant metastasis." (PMID 38203779, 2024). "Beyond their established efficacy in addressing T2D, DPP-4 inhibitors have attracted attention from researchers exploring their potential role in cancer biology." (PMID 39333445, 2024). "For example, a key modulator of PTM in cancer progression is CD26, or dipeptidyl peptidase 4 (DPP4), which is capable of cleaving proteins with an alanine or proline at the NH2 terminus." (PMID 39409924, 2024). "On a more positive note, some clinical data indicated the potential benefits of DPP-4 silencing for certain cancer types, particularly CRC cancer." (PMID 39595655, 2024). "Dipeptidyl peptidase 4 (DPP4) oncogene is frequently expressed in cancer tissue and has been reported to promote cancer development, progression, and metastasis in CRC, making it a potential and novel therapeutic target." (PMID 38203779, 2024). "Other antidiabetics, such as sulfonylureas, alpha-glucosidase inhibitors (AGIs), thiazolidinediones (TZDs), and dipeptidyl peptidase-4 (DPP-4) inhibitors, have been associated with varying levels of cancer risk in LC studies." (PMID 39001440, 2024). "When upregulated in CRC, DPP4 was shown to promote cancer development, progression, and metastasis, making it a potential and novel therapeutic target for CRC." (PMID 38203779, 2024). "Serum soluble CD26/DPP4 titer variation has recently been proposed as a potential prognostic biomarker after a phase I trial in cancer immunotherapy with a humanized anti-CD26 antibody." (PMID 39001488, 2024). "DPP-4 inhibitors have shown anticancer properties in various studies, including their potential to inhibit tumor growth and improve survival rates in cancer patients." (PMID 39333445, 2024). "Beyond metformin, other conventional anti-diabetic treatments, such as insulin, sulfonylureas (SUs), pioglitazone, and dipeptidyl peptidase-4 (DPP-4) inhibitors, have also been examined for their roles in cancer biology, though findings are often inconclusive." (PMID 39595655, 2024). "For example, Dpp4+ASCs, a subtype found in both visceral and subcutaneous adipose tissues, exhibit distinct roles in different cancers." (PMID 37454080, 2023). "The significance of the biomolecule Dipeptidyl peptidase 4/CD26 (DPP4/CD26) has been proposed in elucidating susceptibility to neoplastic growth and coronaviruses, as well as its participation in the immune response, implying that SCRGs may exert a substantial impact on cancer immunotherapy." (PMID 37812215, 2023). "Consistently, previous studies have shown the inhibitory effects of DPP4 knockdown on the proliferation of other cancer cells." (PMID 37907650, 2023). "Following that, we used TIMER to determine clinical consequences of DPP4 expression depending on purity, gender, age, stage, and race in TCGA data from various types of cancer." (PMID 37624423, 2023). "DPP4 is a multifunctional protein that not only has hyperglycemic action, but is also involved in cancer biology processes, such as migration, invasion, metastasis, apoptosis, and sensitivity to chemotherapy." (PMID 37533175, 2023).
cancer (continued). "Taken together, there were significant differences in the effect of DPP4 on the migration and EMT progress among different types of cancer cells, which demonstrated CD26’s complex roles involved in cancer development." (PMID 37907650, 2023). "Further studies such as meta-analyses, long-term studies, and real-world studies are needed to determine if DPP-4 inhibitors affect the incidence of cancer." (PMID 37669959, 2023). "They sought to elucidate the effect of a serine exopeptidase present on most cells called dipeptidyl peptidase 4 (DPP4) that truncates certain chemokines and is upregulated in cancer." (PMID 37587450, 2023). "Several studies in different cancers have found low correlations of sCD26 levels with its enzymatic activity dipeptidyl peptidase 4 (DPP4, EC 3.4.14.5) due to some referenced factors." (PMID 36230486, 2022). "In summary, we revealed that DPP4, CTNNB1, and MET oncogenic signatures are overexpressed in THCA, and are associated with cancer progression, metastasis, resistance, poor disease-free survival, and unfavorable clinical outcomes." (PMID 35205190, 2022). "In particular, dipeptidyl peptidase-4 inhibitors (DPP-4i) have a more complex effect on cancer due to the multi-functional nature of DPP-4." (PMID 35933633, 2022). "At the same time, a thorough follow-up of long-term DPP4 inhibition remains a valuable preventive measure, as the influence of DPP4 on cancer biology remains complex." (PMID 35158891, 2022). "Whereas, the proliferation of cancer cells was reduced when DPP-4 was knocked out or the enzyme activity was inhibited." (PMID 35933633, 2022). "In our study, we analyzed 14 genes that are significantly related to some or most anticancer drugs, such as FANCD2, HSPA5, NFE2L2, ACSL4, and DPP4 in the Cancer Therapeutic Response Portal Database." (PMID 35309947, 2022). "CD26/DPP4 plays an important role in several types of cancer and DPP-4 inhibitors are being evaluated as treatments for cancer." (PMID 35317435, 2022). "DPP-4 inhibition advances the EMT process of cancer cells to a more mesenchymal phenotype, relating to cancer migration, invasiveness, metastasis, chemoresistance, or stemness." (PMID 34063285, 2021). "Using the TIMER analyzer, we found that DPP4 expression was correlated with diverse immune infiltration levels in various cancer types." (PMID 33614513, 2021). "Since other authors have mentioned the favorable effects of DPP-4 suppression for cancer biology elsewhere, this review mainly focuses on the undesirable effects of DPP-4 inhibition in T2DM patients with cancer, including our preclinical data." (PMID 34063285, 2021). "The regulation and function of DPP4 in cancers is complex; DPP4 abundance is reduced in some cancers including gastric, but overexpressed in others including ovarian; and its abundance and activity do not correlate with extent of metabolic inflammation." (PMID 34200333, 2021). "While prior studies have suggested possibly synergistic survival benefits of metformin and DPP4 inhibitors in cancer, data directly comparing the two drugs have been limited." (PMID 34055551, 2021). "The impact of the molecular interplay between the AR and DPP4 is of utmost importance to clarify and further understand the impact of these commonly used diabetic drugs on the most frequent cancer in males." (PMID 34055551, 2021). "Nevertheless, due to such heterogeneities in these preclinical studies, we should be carefully monitoring some potential influences, especially the unfavorable ones, of DPP-4 inhibitors in diabetic patients on cancer chemotherapy." (PMID 34063285, 2021). "The role of Dipeptidyl Peptidase 4 (DPP4) inhibitors has been widely studied in cancer-related research." (PMID 34298800, 2021). "The results were statistically significant despite the small number of cases in the stratified groups, strongly suggesting that serum sCD26/DPP4 titer variation was a definitive prognostic biomarker for cancer patients treated with YS110." (PMID 33757558, 2021).
cancer (continued). "In Pt2, five integrations with total frequencies of more than 1% were observed near or in cancer-related genes (DPP4, TNFAIP3/PERP, MLLT10, EPS8, and SPINT1)." (PMID 34786435, 2021). "We further showed the risk of SARS-CoV-2 infection according to different types of cancers and the expression level of DPP4." (PMID 33614513, 2021). "Observational studies and retrospective studies have discussed the link between DPP-4 inhibitor use and cancer incidence in diabetic patients." (PMID 34063285, 2021). "To further evaluate DPP4 expression in human cancers, we examined RNA-seq data of multiple malignancies in TCGA analyzed by UALCAN, HCCDB, and ENCORI." (PMID 33614513, 2021). "There are several studies about the relationship between DPP-4 inhibitors and site-specific cancer incidence." (PMID 34063285, 2021). "Both a preclinical study and larger clinical studies with a longer term are needed to confirm the safety of DPP-4 inhibitors for cancer incidence." (PMID 34063285, 2021). "Therefore, comparison of the effect of sodium-glucose co-transporter 2 (SGLT2) inhibitors (SGLT2is) as a medication associated with weight loss and metabolic off-load with dipeptidyl peptidase-4 (DPP-4) inhibitors (DPP-4i) as weight-neutral agents could be of interest also in terms of cancer." (PMID 34778040, 2021). "A clinical trial investigating the outcome of chemotherapy, including immune-checkpoint inhibitors, for cancer-bearing diabetic patients with DPP-4 inhibitors is also required." (PMID 34063285, 2021). "The median follow-up periods were also short in order to evaluate the de novo carcinogenetic effect of DPP-4 inhibitors, and the number of cancer cases was limited in these trials." (PMID 34063285, 2021). "The aim of this review is to summarize one unfavorable aspect of DPP-4 inhibitor in cancer-bearing diabetic patients." (PMID 34063285, 2021). "As DPP-4/CD26 has various vital functions in cancer biology, DPP-4 inhibitors potentially act as either suppressors or inducers in cancer development." (PMID 34063285, 2021). "Clinicians should note that the safety of DPP-4 inhibitors for diabetic patients with an existing cancer is an unresolved issue, and further mechanistic analysis is essential in this field." (PMID 34063285, 2021). "The central association marker, DPP4 positively correlated with ACE2 (normal: R 0.308; cancers: 0.382), TMPRSS2 (normal: R 0.524; cancers: 0.382) and FURIN (normal: R 0.498; cancers: R 0.246) in both datasets." (PMID 33796097, 2021). "Some studies described that the DPP-4 inhibitor is correlated with cancer cell invasiveness, metastasis and chemotherapy resistance in certain cancers." (PMID 34063285, 2021). "Patients who are prescribed DPP-4 inhibitors as a second- or third-line anti-diabetic drug often display poor blood glucose control, which potentially promotes cancer initiation." (PMID 34063285, 2021). "As with the association between DPP-4 inhibitor use and newly diagnosed cancer, the conclusions on the effect of DPP-4 inhibitors on cancer prognosis and metastasis differed with factors such as cancer type or patient profile." (PMID 34063285, 2021). "Our data demonstrate that (i) the kidney function in diabetic-cancer patients treated with cisplatin is significantly preserved by using DPP-4 inhibitors, and (ii) the incidence of AKI is reduced by these drugs." (PMID 32084231, 2020). "In parallel, it has been observed a down-regulation of the catabolic enzyme ADA and its cofactor CD26 (also known as dipeptidyl peptidase 4) as well as the reduction of adenosine kinase activity in the cancer microenvironment." (PMID 32708507, 2020).